TMPRSS11B (transmembrane serine protease 11B)
Description:
Serine protease.
Synonyms: HATL5
Tractability: Antibody: UniProt places it where antibodies can reach, with high confidence; its Gene Ontology location is reachable by antibodies, with high confidence; UniProt predicts a signal peptide or a membrane-spanning region.
Gene: Protein-coding gene on chromosome 4 (68,226,653 to 68,245,694, reverse strand). Ensembl gene ENSG00000185873.
Subcellular location: Cell membrane
Gene Ontology:
Molecular function: serine-type peptidase activity; serine-type endopeptidase activity
Biological process: protein processing; proteolysis
Cellular component: extracellular exosome; plasma membrane; extracellular region
Genetic constraint (gnomAD): Loss-of-function variants: 42 observed, 40.4 expected, observed/expected ratio (o/e) 1.04, 90% interval 0.81 to 1.34. The upper end of that interval is the gene's LOEUF score, 1.34, which puts it in group 5 of 6, group 1 being the genes least tolerant of losing a copy. Missense variants: 453 observed, 442.75 expected, observed/expected ratio (o/e) 1.02, 90% interval 0.95 to 1.11. Synonymous variants: 126 observed, 146.36 expected, observed/expected ratio (o/e) 0.86, 90% interval 0.74 to 1.
Homologues: Orthologues: chimpanzee TMPRSS11B (99% identical), macaque TMPRSS11B (93% identical), pig TMPRSS11B (81% identical), rabbit TMPRSS11B (78% identical), zebrafish st14b (28% identical), zebrafish st14a (26% identical), Drosophila melanogaster Sb (26% identical), zebrafish tmprss15 (25% identical), tropical clawed frog tmprss12 (23% identical), Drosophila melanogaster CG1632 (19% identical), Drosophila melanogaster CG10587 (19% identical), Drosophila melanogaster CG17242 (13% identical). Paralogues in human: TMPRSS11A (40% identical), TMPRSS11F (40% identical), TMPRSS11E (39% identical), TMPRSS11D (38% identical), TMPRSS6 (29% identical), HPN (28% identical), TMPRSS3 (28% identical), TMPRSS2 (27% identical), ST14 (26% identical), TMPRSS15 (26% identical), TMPRSS7 (26% identical), TMPRSS13 (26% identical), and 5 more.
Diseases named in the same sentence as TMPRSS11B in open-access papers:
TMPRSS11B is named in the same sentence as 16 diseases in open-access papers, as found by Europe PMC text mining. Sharing a sentence is not in itself a finding about the gene and the disease. The quoted sentences say what the papers report.
head and neck carcinoma (3 papers, 2014 to 2025). A carcinoma that arises from the head and neck region. "In contrast to lung and gastric cancer exhibiting TMPRSS11B overexpression, oral, cervical, esophageal and head and neck carcinomas lack considerable TMPRSS11B expression." (PMID 40508207, 2025). "Thus, in lung and gastric cancer, high TMPRSS11B expression along with Warburg metabolism and forced tumor growth associates with an unfavorable prognosis, whereas in oral, cervical, esophageal and head and neck cancers, it is the lack of TMPRSS11B expression." (PMID 40508207, 2025). "Similar expression pattern was observed for DESC1 in head and neck cancer, and HATL5 (TMPRSS11B) in cervical, esophageal, head and neck cancer." (PMID 28086212, 2017).
lung carcinoma (3 papers, 2024 to 2025). "TMPRSS11B is implicated as a driver of lung carcinoma, and severe COVID-19 is associated with lung abnormalities." (PMID 38375062, 2024). "We next investigated the expression of Tmprss11b in a panel of tumors derived from autochthonous mouse models of lung cancer representing lung adenocarcinoma (LUAD), lung squamous (LUSC), and small cell lung cancer (SCLC)." (PMID 41214366, 2025). "It was recently shown that the presence of TMPRSS11B (also named HATL5) in the BSG-SLC16A3 complex increases the rate of SLC16A3-driven lactate export in lung cancer cells." (PMID 40508207, 2025). "Notably, the proteolytic cleavage of BSG by the sheddase TMPRSS11B was shown to enforce lactate export by SLC16A3 in lung cancer." (PMID 40508207, 2025).
lung squamous cell carcinoma (2 papers, 2021 to 2025). "TMPRSS11B encodes a transmembrane proteinase which was also upregulated in squamous cell carcinoma of the lung." (PMID 34769520, 2021). "TMPRSS11B expression in lung squamous cell carcinoma promotes acidification of the tumor microenvironment due to enhanced lactate transport." (PMID 41214366, 2025). "To test this hypothesis, we used CRISPR/Cas9 to knockout Tmprss11b in KLN205 cells, an established syngeneic mouse model of murine lung squamous cell carcinoma (B and EV1A)." (PMID 41214366, 2025).
COVID-19 (1 paper, 2024). A disease caused by infection with severe acute respiratory syndrome coronavirus 2. "Since SARS-CoV-2 is known to induce pathology in the lung, TMPRSS11B upregulation in individuals with severe COVID-19 may also represent another SARS-CoV-2 pathogenic mechanism." (PMID 38375062, 2024). "The MAL gene, an essential component in NF-κB pathway activation, and serine protease TMPRSS11B were among the top overexpressed genes in our severe COVID-19 cohort (Supplementary 4)." (PMID 38375062, 2024). "In addition, the MAL gene, an important component in NF-κB signaling pathway activation, and TMPRSS11B were among the top 10 upregulated genes in Ghanaians with severe COVID-19." (PMID 38375062, 2024).
mucinous adenocarcinoma (1 paper, 2025). An invasive adenocarcinoma composed of malignant glandular cells which contain intracytoplasmic mucin. "We observed selective enrichment of Tmprss11b in squamous lung tumors but not in mucinous adenocarcinomas or normal lungs." (PMID 41214366, 2025).
cancer (4 papers, 2014 to 2025). A tumor composed of atypical neoplastic, often pleomorphic cells that invade other tissues. "This is underscored by the fact that in SLC16A1/BSG-expressing but TMPRSS11B-deficient cancer cells, the nuclear expression levels of reprogramming factors such as KLF4 are elevated, a condition identified as a hallmark of reverse Warburg cells." (PMID 40508207, 2025). "Accordingly, concepts to treat cancer with inhibitors of BSG sheddases like TMPRSS11B or ADAM12 should be considered with caution, since highly malignant reverse Warburg cells would be supported by such treatments." (PMID 40508207, 2025). "Future studies are warranted to fully elucidate the role of TMPRSS11B in the hillock-like cancer cell state and to identify substrates of this serine protease in normal lung development and in LUSC." (PMID 41214366, 2025). "Given the importance KLF4 in regulating a hillock-like cell state and its regulatory role in a variety of cancers, we sought to determine if TMPRSS11B is induced by KLF4." (PMID 41214366, 2025). "Therefore, TMPRSS11B and its context-dependent role in cancer cell metabolism could be predictive for the prognosis of PDAC patients and the outcome of its therapeutic targeting." (PMID 40508207, 2025). "However, more comprehensive studies are needed correlating the clinical outcome of PDAC patients with TMPRSS11B expression and to understand the role of TMPRSS11B as a prognostic marker in this tumor entity, as already performed in other cancer entities but with contrary findings." (PMID 40508207, 2025). "Thus, TMPRSS11B expression is reciprocal to the highly malignant reverse Warburg cells expressing SLC16A1 and BSG, giving rise to relapse-forming and also metastasizing cancers." (PMID 40508207, 2025). "Consequently, the TMPRSS11B-dependent removal of the two Ig-like domains of BSG leads to a conformational change in the BSG-SLC16A3 interacting region, forcing the export of lactate in these cancer cells." (PMID 40508207, 2025). "Accordingly, the absence of TMPRSS11B promotes the reverse Warburg metabolism in a subset of PDAC cells yielding essential malignant traits including chemoresistance and cancer stemness." (PMID 40508207, 2025). "Moreover, reverse Warburg areas in PDAC patient-derived cancer tissues were identified by high SLC16A1 and BSG expression but absence of TMPRSS11B expression." (PMID 40508207, 2025). "Being essential for the heterogeneity of many malignant tumors, these reverse Warburg cancer cells might differentially contribute to malignant progression depending on the presence of SLC16A1 and BSG as well as the absence of TMPRSS11B." (PMID 40508207, 2025). "Thus, SLC16A1-expressing cancer cells, e.g., in PDAC, acquire a reverse Warburg metabolism preferentially in the absence of TMPRSS11B expression, as supported by our experimental data." (PMID 40508207, 2025).
tumor (4 papers, 2014 to 2025). "Tmprss11b depletion significantly reduces tumor burden in immunocompetent mice and triggers an infiltration of immune cells." (PMID 41214366, 2025). "Here, we evaluate the impact of TMPRSS11B activity on the host immune system and the tumor microenvironment (TME)." (PMID 41214366, 2025). "We previously demonstrated that TMPRSS11B inhibition limits tumor growth of human LUSCs in xenograft assays in immunocompromised NOD/SCID Il2rγ−/− (NSG) mice." (PMID 41214366, 2025). "Collectively, our data demonstrate that LUSC tumors acidify the TME due to their high expression of Tmprss11b, resulting in an immunosuppressive environment that enhances tumor growth." (PMID 41214366, 2025). "Based on our previous demonstration that TMPRSS11B promotes lactate export and the role of lactate in modulating immune cell function, we hypothesized that loss of function of TMPRSS11B would reduce tumor growth and enhance immune cell infiltration in the TME in immunocompetent mice." (PMID 41214366, 2025). "This scenario may explain the contrary findings on TMPRSS11B expression in different tumor entities." (PMID 40508207, 2025). "Based on our prior studies demonstrating a role for TMPRSS11B in promoting tumorigenesis and enhancing lactate export in vitro, we hypothesized that TMPRSS11B expression would promote an immunosuppressive tumor microenvironment in vivo." (PMID 41214366, 2025). "This screen revealed that the transmembrane serine protease TMPRSS11B promotes the transformation of HBECs and enhances LUSC tumor growth in immunocompromised mice." (PMID 41214366, 2025). "Immunohistochemical analysis revealed a reciprocal expression of TMPRSS11B and BSG together with SLC16A1 in some areas of tumor tissues from PDAC patients." (PMID 40508207, 2025). "TMPRSS11B catalytic activity promotes solubilization of Basigin, which enhances MCT4-mediated lactate export, glycolytic flux, and tumor growth, thereby promoting tumorigenesis in LUSC." (PMID 41214366, 2025). "In contrast, other tumor areas exhibiting high expression of TMPRSS11B together with BSG and SLC16A1 were largely negative for KLF4 expression." (PMID 40508207, 2025). "Consequently, tumor cells exhibiting reverse Warburg metabolism would be supported by the absence of TMPRSS1B and thereby the lack of BSG cleavage, as seen in, e.g., T3M4 cells or in Panc1 and BxPc3 cells after knock-down of TMPRSS11B." (PMID 40508207, 2025).
adenocarcinoma (1 paper, 2025). A common cancer characterized by the presence of malignant glandular cells. "We find that the hillock and basal gene signatures were highly enriched in the Tmprss11b-high squamous tumors, while the mucinous gene signature was enriched in the adenocarcinomas (Fig. EV4A,B)." (PMID 41214366, 2025).
TMPRSS11B also shares sentences with these, for which no sentence is quoted: asthma (1 paper); carcinoma of the esophagus (1); cervical carcinoma (1); esophageal cancer (1); gastric cancer (1); glioma (1); lung adenocarcinoma (1); squamous cell carcinoma (1).